TTC3 (tetratricopeptide repeat domain 3)
Description:
E3 ubiquitin-protein ligase which catalyzes the formation of 'Lys-48'-polyubiquitin chains. Mediates the ubiquitination and subsequent degradation of phosphorylated Akt (AKT1, AKT2 and AKT3) in the nucleus. Acts as a terminal regulator of Akt signaling after activation; its phosphorylation by Akt, which is a prerequisite for ubiquitin ligase activity, suggests the existence of a regulation mechanism required to control Akt levels after activation. Positively regulates TGFB1-induced epithelial-mesenchymal transition and myofibroblast differentiation by mediating the ubiquitination and subsequent degradation of SMURF2. Regulates neuronal differentiation by regulating actin remodeling and Golgi organization via a signaling cascade involving RHOA, CIT and ROCK. Inhibits cell proliferation.
Synonyms: DCRR1; RNF105; TPRD; TPRDI; TPRDII; TPRDIII
Tractability: PROTAC: ubiquitination databases record sites on it; its protein half-life has been measured.
Gene: Protein-coding gene on chromosome 21 (37,073,226 to 37,203,112, forward strand). Ensembl gene ENSG00000182670.
Subcellular location: Nucleus; Cytoplasm; Golgi apparatus
Subcellular location (Human Protein Atlas): Nucleoli; Nucleoplasm; Cytosol
Gene Ontology:
Molecular function: protein binding; ubiquitin protein ligase activity; ubiquitin-protein transferase activity
Biological process: protein K48-linked ubiquitination; ubiquitin-dependent protein catabolic process; protein ubiquitination
Cellular component: cytoplasm; nucleus; Golgi apparatus
Genetic constraint (gnomAD): Loss-of-function variants: 123 observed, 170.64 expected, observed/expected ratio (o/e) 0.72, 90% interval 0.62 to 0.84. The upper end of that interval is the gene's LOEUF score, 0.84, which puts it in group 3 of 6, group 1 being the genes least tolerant of losing a copy. Missense variants: 1,634 observed, 1,955.5 expected, observed/expected ratio (o/e) 0.84, 90% interval 0.8 to 0.87. Synonymous variants: 597 observed, 678.83 expected, observed/expected ratio (o/e) 0.88, 90% interval 0.82 to 0.94.
Homologues: Orthologues: chimpanzee TTC3 (96% identical), macaque TTC3 (95% identical), dog TTC3 (83% identical), rabbit TTC3 (80% identical), mouse Ttc3 (75% identical), rat Ttc3 (75% identical), pig TTC3 (73% identical), tropical clawed frog ttc3 (31% identical), zebrafish ttc3 (25% identical).
Diseases named in the same sentence as TTC3 in open-access papers:
TTC3 is named in the same sentence as 35 diseases in open-access papers, as found by Europe PMC text mining. Sharing a sentence is not in itself a finding about the gene and the disease. The quoted sentences say what the papers report.
Down syndrome (11 papers, 2014 to 2023). "Human tetratricopeptide repeat (TPR) domain 3 (TTC3) is a gene located on chromosome 21q22.2 within the Down syndrome (DS) critical region (DSCR); it encodes a protein of 2025 amino acid residues." (PMID 29290964, 2017). "In this report we show that high levels of the TTC3 protein, encoded by one of the genes of the Down Syndrome Critical Region (DCR), prevent neurite extension and disrupt Golgi compactness in differentiating primary neurons." (PMID 24695496, 2014). "It is encoded by the TTC3 gene located in the Down syndrome critical region (DSCR)." (PMID 29290964, 2017). "More broadly, our findings that developmental defects in neurons are triggered by overaccumulated TTC3 protein provide therapeutic implications for cognitive, neurodevelopmental disorders including Down syndrome." (PMID 36917672, 2023). "Mechanistic reasoning regarding the role of TTC3 in CHD warrants reconciliation with the observed increased gene dosage in Down syndrome and the deletion observed in our study." (PMID 31552105, 2019). "For Trisomy 21, current methods include examining the Down Syndrome Critical Region, located on chromosome 21, which contains many genes whose duplication lead to the phenotypic features of Down syndrome, such as Tetratricopeptide Repeat Domain 3 (TTC3) gene." (PMID 28717645, 2017). "Recently, quantitative amplification of the TTC3 gene was shown to discriminate between subjects with Down syndrome from normal subjects; however, this study focused on prenatal and neonatal sources." (PMID 28717645, 2017). "Interestingly, TTC3 is one of the key genes in Down syndrome critical region on 21q22.2, as multiple Down syndrome model mice with TTC3 triplication have been shown to commonly exhibit developmental and cognitive dysfunctions." (PMID 36917672, 2023). "However, TTC3 can express itself above physiological levels in Down’s syndrome (DS) and other neurological diseases, it can disrupt Golgi compactness and impair neurite extension." (PMID 36699066, 2022). "The tetrapeptide repeat domain 3 (TTC3) gene falls within Down's syndrome (DS) critical region." (PMID 33638766, 2022). "TTC3, a ubiquitin E3 ligase, was found to promote the degradation of ubiquitination and phosphorylation of Akt, which is related to the clinical symptoms of Down syndrome." (PMID 34830998, 2021). "TTC3 is highly expressed in mouse at 14.5 days and in human heart tissue; a previous study showed that the gene correlates with cardiac defects in Down syndrome patients, and TTC3 is a novel candidate gene based on array comparative genomic hybridization (aCGH) for 316 nonsyndromic CHD children." (PMID 31552105, 2019). "Interestingly, UFM1, UFL1, and CDK5RAP3 are all key components of the UFMylation pathway which is an ubiquitin-like posttranslational protein modification, while TTC3 is an E3 ubiquitin ligase highly expressed in the CNS and is closely involved in Down syndrome." (PMID 36917672, 2023). "However, if TTC3 is expressed above physiological levels, as it may occur in Down syndrome (DS) and other neurological diseases, besides impairing neurite extension it can also disrupt Golgi compactness." (PMID 24695496, 2014). "Current methods used to study trisomy 21, include detection of the Down’s syndrome critical region (DSCR), which contains many genes such as the tetrapeptide repeat domain 3 (TTC3) gene, that can lead to phenotypic features of DS." (PMID 33638766, 2022). "Ttc3 gene (BSP p-value 2.73e-14, SPARK-X p-value 0.30) is known to play a role in cognitive impairment through protein quality control, which is a common phenotype of Down’s syndrome and Alzheimer’s disease." (PMID 36993309, 2023).
Cognitive impairment (4 papers, 2022 to 2023). Abnormal cognition is characterized by deficits in thinking, reasoning, or remembering. "Ltn1 KO mice showed behavioral deficits associated with cognitive disorders, a subset of which were restored by TTC3 knockdown in medial prefrontal cortex." (PMID 36917672, 2023). "Instead, the aberrantly increased TTC3 protein caused dendritic and synaptic abnormalities associated with cognitive disorders." (PMID 36917672, 2023). "Together, these results indicate that Ltn1 KO mice showed behavioral abnormalities associated with cognitive disorders and a cohort of the behavioral deficits is caused by the aberrantly increased TTC3 protein due to the loss of LTN1." (PMID 36917672, 2023). "Instead, however, we found that the aberrantly accumulated TTC3 protein elicits defects of neurite outgrowth and underlie cognitive disorders in Ltn1 KO mice." (PMID 36917672, 2023). "Remarkably, however, we found that abnormally increased TTC3 protein induced various deleterious effects on neuronal functions; the overaccumulated TTC3 protein in Ltn1 KO neurons and mice results in dendritic and synaptic abnormalities and behavioral deficits associated with cognitive disorders." (PMID 36917672, 2023). "The enhanced protein level of TTC3 reduced not only dendritic outgrowth but also surface-localized GABAAβ3 receptor levels, which would at least partly account for the abnormal behaviors associated with cognitive disorders in Ltn1 KO mice, as suggested previously." (PMID 36917672, 2023). "TTC3 expression is significantly upregulated in DS both in cells, animal models and in humans, resulting in a range of phenotypes, including cognitive impairment." (PMID 33638766, 2022). "Thus, it is unclear what role TTC3 plays in it, but it is certain that targeted interventions in the early stages of cognitive impairment can achieve desirable results." (PMID 33638766, 2022). "Cognitive impairment is a common phenotype of DS and Alzheimer’s disease (AD), and overexpression of TTC3 can accelerate cognitive decline, but the specific mechanism is unknown." (PMID 33638766, 2022).
Alzheimer disease (3 papers, 2017 to 2024). A progressive, neurodegenerative disease characterized by loss of function and death of nerve cells in several areas of the brain leading to loss of cognitive function such as memory and language. "Taken together, this early upregulation of TTC3 may contribute to known metabolic dysfunction through promotion of mitochondrial stress and downregulation of key homeostatic processes and later protein aggregation associated with Alzheimer’s disease development in individuals with T21." (PMID 38357436, 2024). "Some studies have investigated the effect of TTC3 on neuron-related phenotypes, mostly in DS and Alzheimer’s disease (AD)." (PMID 33638766, 2022). "As a result of its interaction with POLG, TTC3 might participate in the maintenance of mitochondrial functions, and mutation or copy number variant of the TTC3 gene may contribute to the pathogenesis of different neurodegenerative diseases, such as DS and Alzheimer disease." (PMID 29290964, 2017).
ischemia (3 papers, 2021 to 2022). A hypoperfusion of the BLOOD through an organ or tissue caused by a PATHOLOGIC CONSTRICTION or obstruction of its BLOOD VESSELS, or an absence of BLOOD CIRCULATION. "High levels of f circ-Ttc3 (which sponges miR-15b) was found to protect cardiomyocytes against ischemia-related apoptotic death." (PMID 35586497, 2022). "The downregulation of Circ-Ttc3 exacerbated post-infarction remodeling in mice, suggesting a protective effect of Circ-Ttc3 on ischemia-related injury." (PMID 34573439, 2021). "The elevation of circ-Ttc3 expression protected cardiomyocytes against ischemia-related apoptotic death, while its downregulation aggravated cardiac dysfunction after MI, which seemed to be possible for the diagnostic and therapeutic targeting circ-Ttc3 in patients with ischemic heart disease (IHD)." (PMID 33670057, 2021).
cognitive decline (2 papers, 2022 to 2024). "Impaired proliferation and neuronal differentiation ability may affect the maturation of the hippocampus, which leads to cognitive decline, suggesting that regulating TTC3 may be a potential strategy for neuroprotection." (PMID 33638766, 2022). "Finally, Ttc3 (tetrapeptide repeat domain 3) is located within the DS critical region, and overexpression of TTC3 can accelerate cognitive decline, but the specific mechanism is unknown." (PMID 39100749, 2024).
gastric cancer (2 papers, 2024 to 2025). A primary or metastatic malignant neoplasm involving the stomach. "Among these, TTC3, a critical E3 ubiquitin ligase, promotes cell cycle progression and tumor cell proliferation in gastric cancer by mediating the ubiquitination and degradation of 14–3-3σ39." (PMID 41315466, 2025). "In summary, these results suggested that PMEPA1 recruited TTC3, allowing it to bind 14-3-3σ and promote its ubiquitin-mediated degradation in gastric cancer cells." (PMID 39607204, 2024). "Hence, whether PMEPA1 recruited TTC3 to bind to 14-3-3σ in gastric cancer cells was investigated." (PMID 39607204, 2024).
Intellectual disability (2 papers, 2014 to 2018). "The most statistically significant association with candidate genes, AGA, DYRK1A, SETD4, and TTC3, was found in mental retardation (adjP = 0.0014)." (PMID 29739397, 2018).
liver fibrosis (2 papers, 2020 to 2024). "Other E3 ligases that are moderately increased upon CCl4-induced liver fibrosis include Rnf4 (ring finger protein 4), Skp2 (S-phase kinase-associated protein 2), Ttc3 (tetratricopeptide repeat domain 3), and Tnfaip3 (tumor necrosis factor alpha-induced protein 3)." (PMID 33261190, 2020). "In summary, our study sheds light on the YY1/KIF18A/TTC3-signaling pathway and its effects on AKT/TOR, providing a basis for future research into liver fibrosis treatment." (PMID 38372748, 2024).
myocardial infarction (2 papers, 2022 to 2024). Gross necrosis of the myocardium, as a result of interruption of the blood supply to the area, as in coronary thrombosis. "Another circRNA, Ttc3, has also been uncovered to modulate the myocardial infarction-induced injury by sponging miR-15b." (PMID 35508616, 2022). "On the contrary, Circ-Ttc3 (Tetratricopeptide Repeat Domain 3) overexpression in cardiomyocytes suppressed apoptosis by sponging the proapoptotic miR-15b, and thus protected against pathological cardiac remodeling post-myocardial infarction." (PMID 39272989, 2024).
Sepsis (2 papers, 2021 to 2022). Sepsis is defined as life-threatening organ dysfunction caused by a dysregulated host response to infection. "Another study on the down-regulation of circRNA TTC3 in sepsis-related AKI showed that up-regulation of circRNA TTC3 can alleviate the sepsis-induced inflammatory response in renal tubular epithelial cells by targeted inhibition of miRNA-148a." (PMID 35755446, 2022).
Anxiety (1 paper, 2023). Intense feelings of nervousness, tension, or panic often arise in response to interpersonal stresses. "Importantly, the decreased anxiety phenotype manifested by the marble-burying test and the defects in nest building capability in Ltn1 KO mice were fully restored by the KD of TTC3." (PMID 36917672, 2023).
diverticulosis (1 paper, 2023). "In the MA GWAS for diverticulosis, rs2835676 (DSCR9 gene) showed strong eQTL association with both transverse and sigmoid colon tissues within the PIGP and TTC3 genes (FDR<3.90E-13)." (PMID 37196047, 2023).
ductal carcinomas (1 paper, 2007). "The genes encoding proteins involved in ubiquitin-mediated proteolysis, such as USP3, RKHD2 and TTC3, and nuclear components, such as DTL, GLCC11, TTC14, FAM54A, HIST1H3B, were upregulated in ductal carcinomas." (PMID 17389037, 2007).
prostate carcinoma (1 paper, 2024). A carcinoma that arises from epithelial cells of the prostate gland. "Mechanistically, PUS1 exerts a non-enzymatic function by directly binding to and stabilizing EIF3b, protecting it from TTC3-mediated ubiquitination and degradation, thereby promoting prostate cancer metastasis." (PMID 39247811, 2024). "In summary, our study confirms that PUS1 interacts with EIF3b, suppressing TTC3-mediated ubiquitination degradation, thereby identifying PUS1 as a novel protective molecule of EIF3b, mediating prostate cancer metastasis both in vitro and in vivo." (PMID 39247811, 2024).
sarcoma (1 paper, 2022). A usually aggressive malignant neoplasm of the soft tissue or bone. "Notably, in a sarcoma study, it was found that a four-gene signature, including DHRS3, JRK, TARDBP, and TTC3, can predict patient survival based on a real-world cohort." (PMID 36231133, 2022).
trisomy (1 paper, 2017). A chromosomal abnormality consisting of the presence of one chromosome in addition to the normal diploid number. "For TTC3, a gene present in chromosome 21, the normal group and Trisomy 18 group had similar threshold cycle values; however, Trisomy 21 group had a threshold cycle about 1.4 cycles lower than the normal group (p < 0.001), suggesting the presence of a gain in chromosome 21." (PMID 28717645, 2017).
cancer (4 papers, 2011 to 2025). A tumor composed of atypical neoplastic, often pleomorphic cells that invade other tissues. "TTC3 is a ubiquitin E3 ligase that promotes ubiquitinated degradation and the phosphorylation of Akt, and is related to the regulation of the cancer cell proliferation rate and the tumor heterogeneity mediated by the β1-integrin/FAK/mTORC2/AKT1-related signaling pathway." (PMID 35053609, 2022). "Notably, genes such as TTC3, TMSB4X, MGST1, DNAJC3, and P4HB are closely linked to cancer cell proliferation and migration and may serve as key regulators of CC progression." (PMID 41315466, 2025). "TTC3 and MARCKSL1 show no cancer gene linking, of which MARCKSL1 are increasedly expressed in some vincristine-resistant cell lines." (PMID 22830977, 2012).
neurological diseases (4 papers, 2011 to 2023). "Beyond these mechanistic insights, our study suggests that TTC3 and UFMylation signaling factors may represent novel therapeutic targets for neurological diseases in which arrested translation is involved." (PMID 36917672, 2023).
tumor (4 papers, 2018 to 2025). "HLTF, ITGA10, PLCG1, and TTC3 are potential tumor antigens of STS for the development of mRNA vaccines." (PMID 35053609, 2022). "However, our study is the first to detail the specific role of TTC3 in EIF3b ubiquitination, providing new insights into the regulatory mechanisms of EIF3b in tumor progression." (PMID 39247811, 2024). "To investigate whether EIF3b serves as a substrate for TTC3-mediated ubiquitination degradation, we transiently transfected TTC3 into tumor cells and observed a significant decrease in endogenous EIF3b protein levels." (PMID 39247811, 2024). "Finally, four potential tumor antigens were identified, each related to prognosis and antigen-presenting cell infiltration in STS: HLTF, ITGA10, PLCG1, and TTC3." (PMID 35053609, 2022).
TTC3 also shares sentences with these, for which no sentence is quoted: syphilis (3 papers); infection (2); acute kidney injury (1); atherosclerosis (1); breast carcinoma (1); cardiovascular diseases (1); cognitive disorder (1); idiopathic pulmonary fibrosis (1); ischemic heart disease (1); lupus nephritis (1); neurodegenerative disease (1); neurodevelopmental disorder (1); Onset (1); renal cell carcinoma (1); triple-negative breast carcinoma (1); trisomy 21 (1).